HBBP1 (hemoglobin subunit beta pseudogene 1)
Synonyms: HBH1; HBHP; HBHps
Gene: Transcribed unprocessed pseudogene on chromosome 11 (5,242,120 to 5,243,537, reverse strand). Ensembl gene ENSG00000229988.
Diseases named in the same sentence as HBBP1 in open-access papers:
HBBP1 is named in the same sentence as 7 diseases in open-access papers, as found by Europe PMC text mining. Sharing a sentence is not in itself a finding about the gene and the disease. The quoted sentences say what the papers report.
COVID-19 (1 paper, 2025). A disease caused by infection with severe acute respiratory syndrome coronavirus 2. "Further, based on results from this study and the COVID-19 host genetics initiative and its update, we further highlight several other genes of interest for our COVID-19 severity hypothesis, namely BCL11A, SLC22A31, SLC6A20, SLC2A5 and HBBP1." (PMID 40240424, 2025).
leukemia (1 paper, 2017). A malignant (clonal) hematologic disorder, involving hematopoietic stem cells and characterized by the presence of primitive or atypical myeloid or lymphoid cells in the bone marrow and the blood. "Because HBG1 and HBG2 are involved in the pathogenesis of hematologic diseases, it is not difficult to imagine that lncRNA- HBBP1 may also be involved in hematologic diseases and even leukemia." (PMID 29221148, 2017).
HBBP1 also shares sentences with these, for which no sentence is quoted: thalassemia (2 papers); hematologic diseases (1); microcytic anemia (1); neonatal anemia (1); red blood cell disorders (1).